TNFAIP8 (TNF alpha induced protein 8)
Diseases named in the same sentence as TNFAIP8 in open-access papers (continued):
Sharing a sentence is not in itself a finding about the gene and the disease.
gastric cancer (continued). "The expression levels of TNFAIP8 were determined in 86 gastric cancer tissue samples and adjacent normal tissues using immunohistochemistry, and in four gastric cancer cell lines and GES-1 cells using reverse transcription-quantitative polymerase chain reaction." (PMID 25936980, 2015). "However, the expression of TNFAIP8 and its clinical significance in gastric cancer remain to be fully elucidated." (PMID 25936980, 2015). "The results demonstrated that the protein levels of TNFAIP8 in the gastric cancer tissues were significantly higher than those of the matched adjacent normal tissues, and there was a close correlation between TNFAIP8 positivity, tumor, necrosis, metastasis stage, and lymph node metastasis." (PMID 25936980, 2015). "In this study, the purpose of this study was to investigate the role of TNFAIP8 in gastric cancer (GC)." (PMID 33682317, 2021). "However, it is difficult to determine whether downregulation of TNFAIP8 also affects gastric cancer cell tumorigenesis." (PMID 25936980, 2015). "In addition, the expression levels of TNFAIP8 may be considered as a biomarker of gastric cancer progression." (PMID 25936980, 2015). "In addition, the expression levels of TNFAIP8 may be considered as a biomarker of gastric cancer." (PMID 32883271, 2020). "TNFAIP8 L1, an independent protective factor for STAD patients identified through multivariate Cox analysis, suppresses invasion and migration by downregulating the Wnt/beta-catenin pathway in gastric cancer." (PMID 34604236, 2021).
lymph node metastasis (6 papers, 2017 to 2022). "We found that high TNFAIP8 expression was associated with advanced pT stage, advanced pTNM stage, lymph node metastasis and unfavourable survival in NSCLC patients." (PMID 30064446, 2018). "TNFAIP8 overexpression was associated significantly with depth of invasion, lymph node metastasis and Lauren classification, and a poorer overall survival in gastric adenocarcinoma patients." (PMID 29108244, 2017). "Similarly, in gastric adenocarcinoma, higher expression of TNFAIP8 is associated with depth of invasion, lymph node metastasis, and poor prognosis." (PMID 30586922, 2018). "For patients with early ESCC, several biomarkers, including PTEN, STMN1, and TNFAIP8, were screened and showed a good ability to predict lymph node metastasis after surgery." (PMID 35903713, 2022). "Our previous study revealed that TNFAIP8 overexpression in ECs correlated with advanced FIGO stage, deep myometrial invasion, lymphovascular space invasion, and lymph node metastasis." (PMID 31043860, 2019).
prostate carcinoma (6 papers, 2014 to 2020). A carcinoma that arises from epithelial cells of the prostate gland. "Expression of TNFAIP8 is strongly associated with the development of various cancers including cancer of the prostate, liver, lung, breast, colon, esophagus, ovary, cervix, pancreas, and others." (PMID 30586922, 2018). "Our study demonstrated that TNFAIP8 is a unique miR-203 target in RAS-mutated prostate cancer cells." (PMID 25004126, 2014). "Interestingly, increased nuclear localization of TNFAIP8 and its interaction with karyopherin alpha 2 in the nucleus is associated with a higher risk of prostate cancer recurrence." (PMID 30586922, 2018). "In prostate cancer cell lines, TNFAIP8 interacts with ATG3 protein and induces autophagy and drug resistance and survival." (PMID 31723944, 2019). "TNFAIP8 overexpression decreased the sensitivity of all prostate cancer cell lines to docetaxel or doxorubicin." (PMID 29928491, 2018). "To confirm the anti-apoptotic role of TNFAIP8 in prostate cancer cells, we transiently expressed TNFAIP8 protein in PC3 cells and treated them with doxorubicin." (PMID 29928491, 2018). "Collectively, these data suggest that TNFAIP8 promotes prostate cancer growth and increased drug resistance by inhibiting cellular apoptosis." (PMID 29928491, 2018). "In conclusion, this study provides first-time evidence that TNFAIP8 protein participates in the initiation of cellular autophagy and modulates cell survival in prostate cancer cells." (PMID 29928491, 2018). "We investigated the role of TNFAIP8 in the regulation of the cell cycle, autophagy, cell survival and neuroendocrine differentiation in prostate cancer cells." (PMID 29928491, 2018). "Previous studies showed that activation of the autophagy signaling pathway contributes to neuroendocrine differentiation in prostate cancer cells, and our results demonstrated that TNFAIP8-induced autophagy was not limited to prostate cancer cells." (PMID 29928491, 2018). "Because TNFAIP8 has been reported to have anti-apoptotic properties, we confirmed the anti-apoptotic role of TNFAIP8 in prostate cancer cells." (PMID 29928491, 2018). "We investigated the role of TNFAIP8 in cell survival using a cell colony formation assay and by measuring cell proliferation in three prostate cancer cell lines." (PMID 29928491, 2018). "Collectively, our findings reveal that by the creation of cellular autophagy events, TNFAIP8 promotes cell survival and drug resistance in prostate cancer cells." (PMID 29928491, 2018). "In an earlier study, we demonstrated that TNFAIP8 induces autophagy in prostate cancer cells." (PMID 32152268, 2020). "Depletion of TNFAIP8 in prostate cancer cells increases anti-proliferation and apoptosis-related genes such as IL24, FAT3, LPHN2, and EPHA3, fatty-acid oxidation gene, ACDL, and decreases the expression of several oncogenes including NFAT5, MALAT1, MET, FOXA1, KRAS, S100P and OSTF1." (PMID 31723944, 2019). "In response to androgen, an induction of TNFAIP8 protein is reported in prostate cancer cells." (PMID 30586922, 2018). "Recently, using Microarray analysis, we have shown that expression of TNFAIP8 in PC3 prostate cancer cells downregulates the mRNA expression of several cell cycle-related genes, including CCNB2, CCNE2, CDK2, CHEK, and PCNA, however, no major cell cycle changes were observed." (PMID 30586922, 2018). "We also showed that TNFAIP8 increased resistance to the anticancer drugs, docetaxel, and doxorubicin, and promoted cell proliferation and cell growth in prostate cancer cells through the inactivation of cellular apoptosis and the induction of cellular autophagy." (PMID 29928491, 2018). "In addition, by activation of autophagy, TNFAIP8 modulates the expression of neuroendocrine differentiation protein markers in prostate cancer cells." (PMID 29928491, 2018).
prostate carcinoma (continued). "Collectively, the data suggest that the activation of cellular autophagy by TNFAIP8 might be involved in the neuroendocrine differentiation in prostate cancer cells." (PMID 29928491, 2018). "Here, we demonstrated that TNFAIP8 expression induced expression of the NED biomarkers chromogranin A and synaptophysin in prostate cancer cells; however, the exact mechanism by which TNFAIP8 induces NED in prostate cancer cells remains unclear." (PMID 29928491, 2018). "Recently, using immunoprecipitation assay, we demonstrated that TNFAIP8 interacts with ATG3 and facilitates autophagy in prostate cancer cells." (PMID 30586922, 2018). "Because TNFAIP8 is a TNFα-inducible protein, we confirmed the expression and identity of TNFAIP8 isoforms by treating three prostate cancer cell lines (PC3, LNCaP, and C4-2) with TNFα and analyzing the induction of TNFAIP8 isoform proteins." (PMID 29928491, 2018). "Because our data showed that TNFAIP8 modulated autophagy markers, we hypothesized that TNFAIP8 may interact with ATG3 or other autophagy-related proteins in prostate cancer cells." (PMID 29928491, 2018).
cervical cancer (5 papers, 2014 to 2020). A primary or metastatic malignant neoplasm involving the cervix. "In cervical cancer, it revealed that the GG genotype of TNFAIP8 rs11064 was connected with an elevated risk compared with AA/AG genotypes." (PMID 32821249, 2020). "Research has indicated the relationship of TNFAIP8 gene polymorphisms with susceptibility of cervical cancer." (PMID 31043860, 2019). "Our results suggest that the rs11064 polymorphism positively correlated with TNFAIP8 protein expression, being consistent with that in cervical cancer." (PMID 31043860, 2019). "TNFAIP8 rs11064 polymorphism especially the variant G allele was associated with cervical cancer risk in Chinese people, indicating a risk allele." (PMID 31043860, 2019). "TNFAIP8 expression in the survival subset of cervical cancer patients is significantly associated with resistance to cisplatin and nedaplatin, recurrence, and death from cervical cancer." (PMID 30586922, 2018). "In cervical cancer, it attempted to explore the relationship between TNFAIP8 rs11064 polymorphism and drug resistance, but with no sense." (PMID 32821249, 2020).
esophageal squamous cell carcinoma (5 papers, 2012 to 2020). Esophageal squamous cell carcinoma (ESCC) is a type of esophageal carcinoma (EC) that can affect any part of the esophagus, but is usually located in the upper or middle third. "TNFAIP8 expression is strongly associated with MMP9 and Ki-67 expression in endometrial tumor cells and depletion of TNFAIP8 in esophageal squamous cell carcinoma cells induced cisplatin mediated apoptosis." (PMID 31723944, 2019). "The clinical relevance of TNFAIP8 was also determined in esophageal squamous cell carcinoma: higher expression of TNFAIP8 co-relates with TNM stage, tumor depth, lymph node metastasis, distant metastasis, lymphatic invasion, and venous invasion among ESCC patients, as well as with poor survival." (PMID 30586922, 2018). "In esophageal squamous cell carcinoma (ESCC), overexpression of TNFAIP8 was found in 59.8% tumor specimens, and the 3-year lymphatic metastatic recurrence rate among TNFAIP8-overexpressing patients was significantly higher than in TNFAIP8 lower-expressing patients or TNFAIP8-negative patients." (PMID 30586922, 2018).
liver cancer (5 papers, 2018 to 2024). An epithelial or non-epithelial malignant neoplasm that arises from the liver. "Our data suggest that TNFAIP8 enhances liver cancer cell survival and clonogenic potential, and increases resistance against anti-liver cancer drugs, sorafenib, and regorafenib by downregulation of cell apoptosis." (PMID 32152268, 2020). "To further investigate the role of TNFAIP8 in liver cancer, we analyzed the expression of TNFAIP8 mRNA and protein levels in four HCC cell lines." (PMID 32152268, 2020). "We also analyzed the expression of TNFAIP8 and LC3β I/II in different stages of liver cancer tumors." (PMID 32152268, 2020). "In conclusion, our data showed that higher expression of TNFAIP8 increased cell steatosis and autophagy in liver cancer cells." (PMID 32152268, 2020). "We performed immunohistochemical staining to assess TNFAIP8 protein expression levels in different stages of liver cancer." (PMID 32152268, 2020). "In the current study, we analyzed the expression profile of TNFAIP8 isoforms in prostate, breast, and liver cancer cell lines and found that isoform 2 is the predominantly expressed isoform in prostate and liver cancer cells." (PMID 29928491, 2018). "The role of TNFAIP8 in liver cancer remains elusive, and only a few reports suggest that TNFAIP8 is involved in liver carcinogenesis." (PMID 30586922, 2018). "TNFAIP8 also induced autophagy and steatosis in liver cancer cells." (PMID 32152268, 2020). "The study reveals that TNFAIP8 promotes liver cancer growth through LATS1-YAP signaling." (PMID 30586922, 2018). "The biological significance of the D-Box consensus present in TNFAIP8 proteins is still unknown, but a recent study demonstrates that TNFAIP8 modulates cell cycle (S–phase) in liver cancer cells." (PMID 30586922, 2018). "Moreover, inactivation of autophagy by 3-MA and treatment with anti-liver cancer drugs sorafenib or regorafenib in HCC cells significantly prevented TNFAIP8-mediated cell survival, suggesting that TNFAIP8-mediated induction of autophagy is required for cell survival and drug resistance in HCC cells." (PMID 32152268, 2020). "Here we investigated whether TNFAIP8 modulates autophagy in liver cancer cells." (PMID 32152268, 2020). "We investigated the molecular mechanism by which TNFAIP8 modulates early liver diseases or HCC progression using in vivo mouse models or in vitro using HCC cell models and liver cancer patient’s (TMA) samples." (PMID 32152268, 2020). "TNFAIP8 regulates Hippo signaling in lung and liver cancer cells by interaction with LATS1, and expression of TNFAIP8 induces cell proliferation, migration, invasion, and xenograft tumor growth." (PMID 31723944, 2019). "The protein expression of TNFAIP8 isoforms was analyzed in PC3, LNCaP, MDA-MB-468, and LLC1 cells and human liver cancer cells (HepG2) by immunoblotting." (PMID 29928491, 2018).
non-small cell lung carcinoma (5 papers, 2012 to 2022). A group of at least three distinct histological types of lung cancer, including non-small cell squamous cell carcinoma, adenocarcinoma, and large cell carcinoma.
hepatocellular carcinoma (4 papers, 2017 to 2023). A malignant tumor that arises from hepatocytes. "In this study, we demonstrated that TNFAIP8 protein was upregulated in human hepatocellular carcinoma and associated with malignant clinical parameters." (PMID 28152516, 2017). "Here we define the role of TNFAIP8 in early events associated with development of hepatocellular carcinoma (HCC)." (PMID 32152268, 2020). "TNF Alpha Induced Protein 8 (TNFAIP8) was showed to increase cell survival and decrease apoptosis in hepatocellular carcinoma cells." (PMID 37798647, 2023). "On the other hand, induction of TNFAIP8 by insulin inhibits autophagy by the formation of TNFAIP8-phosphatidylethanolamine (PE)-Gαi3 ternary complex in mouse hepatoma Hepa-1-6 cells." (PMID 32152268, 2020). "Knockdown of LATS1 or YAP by siRNA blocked the effects of TNFAIP8 on cell proliferation, suggesting that TNFAIP8 promotes hepatocellular carcinoma progression through LATS1-YAP signaling pathway." (PMID 30586922, 2018). "Although TNFAIP8 overexpression has been implicated in several human cancers, its clinical significance and biological function in hepatocellular carcinoma (HCC) remains unknown." (PMID 28152516, 2017). "In hepatocellular carcinoma, TNFAIP8 interacts with large tumor suppressor kinase 1 (LATS1), a serine/threonine-protein kinase, and overexpression of TNFAIP8 inhibits Yes-associated protein (YAP) phosphorylation, resulting in nuclear localization and stabilization of YAP." (PMID 30586922, 2018).
pancreatic cancer (4 papers, 2018 to 2026). "TNFAIP8 expression in pancreatic cancer tissue correlates with expression of epithelial growth factor receptor, and the study suggests that expression of TNFAIP8 in pancreatic cancer tissue is higher than normal pancreas tissue, indicating that TNFAIP8 promotes pancreatic cancer." (PMID 30586922, 2018).
Sepsis (4 papers, 2017 to 2023). Sepsis is defined as life-threatening organ dysfunction caused by a dysregulated host response to infection. "The expression of TNFAIP8 also affects the polarization of splenic CD4+ T lymphocytes after sepsis, suggesting that TNFAIP8 regulates the pathogenesis of splenic T lymphocyte immune dysfunction in mice." (PMID 34925463, 2021). "In the comparison between septic shock and sepsis groups, we found hypomethylation of IL1B (septic shock group 20% hypomethylated compared to sepsis group) and TNFAIP8 (septic shock group 10% hypomethylated compared to sepsis group)." (PMID 38235139, 2023).
colon cancer (3 papers, 2020 to 2021).
COVID-19 (3 papers, 2023 to 2025). A disease caused by infection with severe acute respiratory syndrome coronavirus 2. "At the genetic level, COVID-19 hospitalization and MS share five risk genes within two loci, including TNFAIP8, HSD17B4, CDC37, PDE4A, and KEAP1, which may mediate the association between MS and COVID-19." (PMID 37395896, 2023). "The results revealed various diseases from the common DEGs of AKI, CKD, and COVID-19, which include DUSP6, NRIP1, TNFAIP8, S1PR1, and TANK." (PMID 37026010, 2023). "By 6 weeks post-inclusion (T2), COVID-19 hypermethylation of genes with lowest p-value included NXN, FMNL2, ZBTB46, SLC35F3, and SHQ1, and the hypomethylated genes included ELMO1, XBP1, GRIK1, TNFAIP8, and SH3BP5." (PMID 41227320, 2025). "By 6 weeks post-inclusion, COVID-19 hypermethylation of genes with the highest fold-change compared to healthy controls included FAM178B, FYN, TMCC1, TMEM212-AS1, and FIG4, while the top five hypomethylated genes were GIT2, PDGFRB, SEMA6D, TNFAIP8, and ETV6." (PMID 41227320, 2025).
ovarian carcinoma (3 papers, 2020 to 2026). A malignant neoplasm originating from the surface ovarian epithelium. "This research aimed to investigate the association between tumor necrosis factor-a-induced protein 8 (TNFAIP8) polymorphisms and ovarian cancer (OC) susceptibility." (PMID 32821249, 2020). "Additionally, TNFAIP8 expression is markedly increased in platinum‐resistant tumors versus normal ovarian tissue, indicating that TNFAIP8 is associated with ovarian cancer drug resistance." (PMID 40968783, 2026). "TIPE1, a newly identified member in TIPE (TNFAIP8) family, plays an important role in tumorigenesis and immune regulation, but its role in ovarian cancer, especially in tumor metastasis, remains unknown." (PMID 34188681, 2021).
colitis (2 papers, 2018 to 2020). Inflammation of the colon. "Knocking out the Tnfaip8 gene exacerbated disease in a dextran sodium sulfate (DSS) model of murine colitis." (PMID 32613168, 2020). "The increased mortality in TNFAIP8 knockout mice with colitis could be explained by increased cell death, and decreased proliferation of colonic epithelial cells." (PMID 32613168, 2020).
diabetes (2 papers, 2020 to 2024). "Aiming to deeply analyze the relationships of TNFAIP8 genotypes with OC susceptibility, we divided age into ≤ 54 years old and > 54 years old, whether smoking, whether complication (patients with diabetes and cardio-cerebrovascular disease), and whether there is family history of OC." (PMID 32821249, 2020).
melanoma (2 papers, 2021). A malignant, usually aggressive tumor composed of atypical, neoplastic melanocytes. "Comparing the high and low expression levels of TNFAIP8 in skin melanoma patients with Kaplan–Meier OS curves by PrognoScan (GSE19234), high TNFAIP8 expression levels were also corresponded with good OS prognosis in melanoma (n = 42, p = 0.002)." (PMID 34925463, 2021).
renal carcinoma (2 papers, 2020 to 2025). A carcinoma arising from the epithelium of the renal parenchyma or the renal pelvis. "Currently, tumor necrosis factor-α-induced protein 8 (TNFAIP8/TIPE) is a newly discovered tumorigenesis factor, and TNFAIP8 and the EMT influence the migration of renal cancer cells." (PMID 32226521, 2020).
steatosis (2 papers, 2020 to 2025). Increased lipid within the cytoplasm of cells. "TNFAIP8 binds to fatty acids, regulates the expression of enzymes involved in lipid and fatty acid metabolism, and modulates autophagy and cellular steatosis." (PMID 40057782, 2025). "The biological significance of TNFAIP8-mediated induction of autophagy, as well as the subsequent induction of cell steatosis was further examined in the obese mouse model and chronic EtOH fed mouse model." (PMID 32152268, 2020). "Next, we analyzed the role of TNFAIP8 in EtOH-mediated cell steatosis in HCC cells and hepatic steatosis in mice fed chronic EtOH." (PMID 32152268, 2020). "Chronic feeding of mice with alcohol increased hepatic levels of TNFAIP8, autophagy, and steatosis but not in high-fat-fed obese mice." (PMID 32152268, 2020).